LSMEM2 (leucine rich single-pass membrane protein 2)
Synonyms: C3orf45; FLJ38608
Tractability: Antibody: UniProt predicts a signal peptide or a membrane-spanning region; the Human Protein Atlas places it where antibodies can reach.
Gene: Protein-coding gene on chromosome 3 (50,279,030 to 50,288,116, forward strand). Ensembl gene ENSG00000179564.
Subcellular location: Membrane
Subcellular location (Human Protein Atlas): Plasma membrane
Gene Ontology:
Molecular function: protein binding
Cellular component: membrane
Genetic constraint (gnomAD): Loss-of-function variants: 20 observed, 18.16 expected, observed/expected ratio (o/e) 1.1, 90% interval 0.77 to 1.59. The upper end of that interval is the gene's LOEUF score, 1.59, which puts it in group 6 of 6, group 1 being the genes least tolerant of losing a copy. Missense variants: 207 observed, 223.68 expected, observed/expected ratio (o/e) 0.93, 90% interval 0.82 to 1.04. Synonymous variants: 94 observed, 101.26 expected, observed/expected ratio (o/e) 0.93, 90% interval 0.79 to 1.1.
Homologues: Orthologues: chimpanzee LSMEM2 (99% identical), macaque LSMEM2 (88% identical), rabbit LSMEM2 (79% identical), mouse Lsmem2 (76% identical), rat Lsmem2 (75% identical), dog LSMEM2 (71% identical), pig LSMEM2 (70% identical).
Diseases named in the same sentence as LSMEM2 in open-access papers:
LSMEM2 is named in the same sentence as 2 diseases in open-access papers, as found by Europe PMC text mining. Sharing a sentence is not in itself a finding about the gene and the disease. The quoted sentences say what the papers report.
heart failure (2 papers, 2023 to 2025). Inability of the heart to pump blood at an adequate rate to meet tissue metabolic requirements. "Indeed, LSMEM2 as a CM‐restricted cell surface protein has been highlighted negatively associated with human heart failure, and potential region‐specific marker for discriminating cellular phenotypes and disease states." (PMID 39790063, 2025). "For example, we observed that the abundance of LSMEM2 in cardiomyocytes decreases with heart failure." (PMID 36950336, 2023).
cardiac diseases (1 paper, 2025). "We identifiedeight proteins exclusive to the exposure group PR, with leucine-richsingle-pass membrane protein 2 (LSMEM2) and MRPL2 showing significantassociations with cardiac diseases." (PMID 39841981, 2025).